ZBTB16 (zinc finger and BTB domain containing 16)
Diseases named in the same sentence as ZBTB16 in open-access papers (continued):
Sharing a sentence is not in itself a finding about the gene and the disease.
cancer (58 papers, 2007 to 2025). A tumor composed of atypical neoplastic, often pleomorphic cells that invade other tissues. "In relation to ZBTB16's repressive nature, GR activation leads to epigenetic remodeling and loss of histone acetylation at sites proximal to cancer‐driving genes." (PMID 37902007, 2023). "This is supported by studies in other cancer types where ZBTB16 has been associated with growth arrest and diminished cancer growth." (PMID 37902007, 2023). "The seven ZBTB16‐RARA‐positive patients were then screened for additional mutations using whole exome sequencing (n = 3) or an extended cancer panel including 409 genes (n = 4)." (PMID 34042280, 2021). "In this comprehensive pan cancer analysis, we found the expression patterns of ZBTB16 in multiple types of cancer." (PMID 40552012, 2025). "The results showed that ZBTB16 was significantly downregulated in 15 types of cancer and overexpressed in one type of cancer." (PMID 40552012, 2025). "The ectoderm panel of transcription factors showed that ZBTB16 (zinc finger and BTB domain-containing protein 16) was significantly overexpressed in MSCs compared to cancer cells and iPSC lines." (PMID 39621192, 2025). "This study conducted a pan cancer analysis of ZBTB16 in the TCGA database for the first time, showing that it was lowly expressed in 15 types of cancer and highly expressed in one type of cancer." (PMID 40552012, 2025). "In contrast, cell apoptosis of the ZBTB16 overexpressing cell line treated with PPI was significantly higher than that of the PPI group, indicating that ZBTB16 had a key contribution in the anti-cancer effects of PPI." (PMID 39182119, 2024). "This multifaceted regulation positions ZBTB16 as an important suppressor of tumorigenesis, underscoring its potential significance in maintaining cellular homeostasis and cancer growth regulation." (PMID 37902007, 2023). "Seven winning TFs (ETV4, ID2, MEIS1, NR4A3, RARA, TCF3, and ZBTB16) are related to transcriptional misregulation in cancer (p-value: 6.9 × 10−5)." (PMID 36101460, 2022). "Among the top enriched cancer genes in cluster 2, ZBTB16 can inhibit inflammatory response 38, resulting in a low inflammasome score in this cluster." (PMID 34815793, 2021). "In silico analyses of The Cancer Genome Atlas data sets revealed consistent correlations between the expression of the transcripts encoding LRIG1 and its interactors ZBTB16 and PTPRK and inverse correlations between the transcripts encoding LRIG1 and GLRX3." (PMID 29317492, 2018). "Notably, TOP2A and ZBTB16 are the most frequently upregulated and downregulated ER genes, respectively, across various cancer types." (PMID 41431699, 2025). "However, our study also revealed that the expression of ZBTB16 varies depending on different types of cancer, and it has the potential to be used as a biomarker for malignancy detection." (PMID 40552012, 2025). "We analyzed a group of genes that were upregulated in MSC lines compared to cancer cell lines, including transcription factors (ZBTB16, HAND2, and TWIST1), a cadherin regulating cell adhesion (CDH20), a receptor tyrosine kinase (PDGFR-α), and a negative cell cycle regulator (CDKN2A)." (PMID 39621192, 2025). "KLF4 and ZBTB16 are the two common downregulated TFs in the three types of cancer that might control key overregulated TFs and DEGs, and therefore, their expression must be controlled by key overregulated TFs during the tumorigenic process." (PMID 39228892, 2024). "We found seven upregulated genes (MCM10, RAD51-associated protein 1 (RAD51AP1), KIF2C, Y_RNA, FAM64A, CDC6, and CDCA8) and six downregulated genes (ADAMTS8, ATP1A2, MYH1, OGN, OMD, and ZBTB16) in at least two phenotypes containing either ALT high/middle or TEL high/middle regardless the cancer type." (PMID 38763334, 2024).
cancer (continued). "Importantly, expression of ZBTB16 itself was predictive of survival in patients with luminal A cancer, with high expression relating to favorable PFS and low expression to poor PFS, the latter with comparable outcomes as observed for luminal B subtype." (PMID 37902007, 2023). "As higher mRNA expression of the transcriptional repressor ZBTB16 is observed in normal breast tissue in comparison to primary tissue, with further decrease in luminal B cancers (Fig EV5A), we sought to further understand the role of ZBTB16 in ER‐positive breast cancer." (PMID 37902007, 2023). "Importantly, as we show here, loss of GR activity leads to the absence of ZBTB16 expression—a crucial hormone‐driven regulator of cancer growth." (PMID 37902007, 2023). "Another case is an ncORF in ZBTB16 (CNIT score 0.7), which was differentially expressed in three of the cancers which samples had peptide support (BRCA, EOGC, CCRC)." (PMID 37275273, 2023). "On the contrary, negative LASSO coefficients were found for the genes ADRB2, CRYAB, NR4A1, CMTM5, ZBTB16, SYNE3, and RAD51, which were downregulated in cancer compared with normal samples." (PMID 36552262, 2022). "It is worth mentioning that ZBTB16 and FOXO1 were also involved in the pathways in cancer according to the KEGG analysis." (PMID 29439675, 2018). "Genes labeled by IPA as being cancer related (COL18A1, STAT5B, CTDSPL) were also involved with infection as were genes involved in apoptosis and growth (CTDSPL, POLR2F, ZBTB16)." (PMID 18047719, 2007). "K-M survival analysis demonstrated that the expression of ZBTB16 was related closely to overall survival (OS) of the HCC patients, with high expression indicating better survival, especially in patients with stages III- IV cancers." (PMID 39182119, 2024). "We compared the expression of the 15 immune gene cancer tissues and adjacent tissues in the TCGA-BLCA cohort and found that the expression of the CCR9, IL7, PTGER4, IL10, CTSG, and ZBTB16 proteins in the adjacent tissues was significantly higher than that in the cancerous tissues (P < 0.05)." (PMID 32655621, 2020). "However, the KEGG pathway “Transcriptional misregulation in cancer” were represented with four genes mapping to the pathway (Bcl6, Zbtb16, Aff1, and Dusp6), but not significant (adj." (PMID 34428250, 2021). "Importantly, the glucocorticoid‐induced upregulation of ZBTB16 is not exclusive for MCF‐7, and is also seen in T47D cells; another model derived from a luminal A cancer (scRNA‐sequencing time course; Fig EV4J)." (PMID 37902007, 2023).
infection (10 papers, 2007 to 2023). The state of being infected such as from the introduction of a foreign agent such as serum, vaccine, antigenic substance or organism. "Only 5 cellular genes (Cyp1a1, Ltf, Nr4a3, Per2 and Zbtb16) were significantly modulated on day 1 post-infection." (PMID 35812400, 2022).
metabolic disease (3 papers, 2023). A congenital disorder (due to inherited enzyme abnormality) or acquired (due to failure of a metabolically important organ) disorder resulting from an abnormal metabolic process. "It was demonstrated that ZBTB16 plays a role in cellular bioenergetics and in autophagy by mediating the proteasomal degradation of autophagic protein Atg14L, and in the pathogenesis of metabolic diseases." (PMID 37626062, 2023). "ZBTB16 belongs to the promyelocytic leukemia zinc finger family and is a multifaceted signaling hub for a number of cellular processes and was recently presented to be involved in the pathogenesis of metabolic diseases by regulation of cell bioenergetics." (PMID 37626062, 2023). "Zbtb16, also known as promyelocytic leukaemia zinc finger protein (PLZF), is a transcription repressor involved in energy metabolism maintenance and pathogenesis of metabolic diseases." (PMID 36768453, 2023).
digestive system tumors (1 paper, 2024). "Recent studies have reported that ZBTB16 is also associated with a variety of digestive system tumors." (PMID 38789960, 2024). "Recent studies have revealed that ZBTB16 is also associated with various digestive system tumors." (PMID 38789960, 2024).
skeletal dysplasia (1 paper, 2021). Any Mendelian diseases that affects growth and development of the skeleton. "Zbtb16 KO mice showed skeletal dysplasia and smaller body size compared with wild-type (WT) mice, due to a single nucleotide (lu) mutation in Zbtb16, resulting in a nonsense mutation (p.Arg234*)." (PMID 33895774, 2021).
ZBTB16 also shares sentences with these, for which no sentence is quoted: colon cancer (7 papers); HCMV infection (5); pancreatic cancer (5); glioblastoma (4); Hypertension (4); lymph node metastasis (4); colorectal cancer (3); lung adenocarcinoma (3); thyroid carcinomas (3); Azoospermia (2); cardiovascular disease (2); clear cell renal cell carcinoma (2); colitis (2); cryptorchidism (2); depression (2); Fanconi Anaemia (2); gallbladder cancer (2); hypospadias (2); malaria (2); metastatic prostate carcinoma (2); nasopharyngeal carcinoma (2); neurodegenerative disease (2); papillary thyroid carcinoma (2); Stroke (2); T-cell acute lymphoblastic leukemia (2); triple-negative breast carcinoma (2); acute lymphoblastic leukemia (1); Alzheimer disease (1); anaplastic thyroid carcinoma (1); Arthritis (1).
A further 65 diseases each share a sentence with ZBTB16 in 1 paper.